BDNF (brain derived neurotrophic factor)
Diseases named in the same sentence as BDNF in open-access papers (continued):
Sharing a sentence is not in itself a finding about the gene and the disease.
depression (continued). "Accumulating evidence suggests that BDNF could play an important role in the treatment of depression; however, the biochemistry has not been defined." (PMID 34950248, 2021). "In this article, we provide direct evidence that Pdcd4 impairs synaptic plasticity and consequently results in the depression-like behaviors through suppression of BDNF mRNA translation in response to CRS, suggesting Pdcd4 might be a potential target for depression therapy." (PMID 32203159, 2021). "Although some studies showed that tDCS can induce an increase in serum BDNF levels in opioid-addicted patients or in patients with Parkinson’s disease, others did not detect any effects of tDCS on BDNF levels in patients with major depressive disorder and bipolar disorder." (PMID 34069556, 2021). "In addition, the role of BDNF in the pathophysiology of DD is supported by the finding of a significant negative correlation of BDNF with depression severity (CDI) (p ≤ 0.001) in our pediatric patients." (PMID 33801688, 2021). "In contrast, SFN did not affect the protein expression of BDNF and its transcriptional repressor proteins in the medial prefrontal cortex (mPFC) and hippocampus, nor did it reduce depression-like behaviors and abnormal synaptic transmission in Nrf2 knockout mice." (PMID 33627628, 2021). "Unlike NGF and BDNF, there are not many studies currently examining NT-3 and NT-4/5 in depression." (PMID 34393735, 2021). "However, several studies showed a relationship between the severity of depression symptoms and the concentration of BDNF presenting it as a negative correlation." (PMID 33804468, 2021). "The connecting link between depression and T2DM might be BDNF." (PMID 34215825, 2021). "Given that the decrease of BDNF expression was found in the mTBI-J treated animals, we examined whether an administration of TrkB agonist 7,8-DHF could lessen or prevent the mTBI-J treatment-induced depression-like behaviors." (PMID 34959450, 2021). "Notably, we emphasized that BDNF-TrKB but not DA signaling in the VTA–NAc circuits is important for the development of depression-like behaviors." (PMID 34577589, 2021). "Many hypotheses such as inflammatory cytokines, hypothalamic pituitary adrenal (HPA) axis, neurotransmitter system, brain-derived neurotrophic factor (BDNF) in the brain and endogenous metabolites are involved in depression pathogenesis, but it is still obscure." (PMID 34867405, 2021). "Due to the multifaceted pathogenesis of depression, this study aimed to clarify whether the KBD formula ameliorated the effect of UCMS-induced changes in expression levels of the depression-related genes BDNF, CREB, GR, SGK1, FKBP5, IL-1β, IL-6, and TNF-α." (PMID 34358084, 2021). "The increase in 5-HT, BDNF, and GLP-1 in depressive-like patients may help ameliorate depression." (PMID 35010973, 2021). "In the same direction, animal models of depression such as the chronic unpredictable/mild stress have shown that vulnerable animals that develop depression-like behaviors after exposure to the stressor show a significant reduction in hippocampal BDNF expression, as opposed to resilient animals." (PMID 33578758, 2021). "However, an elevated level of serum BDNF levels was found in depressed patients but did not correlate with the severity of depression or suicidality." (PMID 33801688, 2021). "Nevertheless, the relationship between regular physical activity, cognitive factors (plasma nerve growth factor (NGF), brain-derived neurotrophic factor (BDNF), and cathepsin B levels), and psychological parameters (the climacterium, depression, and cognition) has not yet been investigated." (PMID 33233633, 2020). "Therefore, decreased BDNF may contribute to reduced SST expression and behavioral symptoms of depression." (PMID 33192369, 2020).
depression (continued). "Moreover, a correlation analysis revealed a negative relation between depression and NT-4 (r = −0.330, p = 0.005), and a weak negative relation between anxiety and BDNF or NT-4 (r = −0.268, p = 0.023 or r = −0.259, p = 0.028) in METH addicts." (PMID 32210759, 2020). "ERK, alongside BDNF, has shown to be downregulated in the PFC and hippocampus of depressed humans and animals, and antidepressants could, in turn, reverse the hypoactivity of ERK and alleviate depression-like behaviors." (PMID 33329109, 2020). "However, in spite of these functional consequences, systematic reviews of the results of association studies suggest that this BDNF genotype does neither exert a major influence on the development of depression, nor on the serum BDNF levels." (PMID 32116853, 2020). "To date, all prior studies investigating the effects of the BDNF Val66Met polymorphism on EEG frequency spectra have done so in a clinical context (e.g., sleep deprivation, depression), with no studies characterising BDNF Val66Met genotypic differences in EEG spectra in a neurotypical context." (PMID 33087740, 2020). "However, unlike the consistent results in major depressive disorder, findings related to BDNF in GAD remain controversial." (PMID 32824625, 2020). "The pathogenesis of depression is not yet complete, but some major hypotheses have been proposed: hippocampal neurogenesis and the BDNF/TrkB pathway may be involved in the pathophysiology of depression." (PMID 32477150, 2020). "However, not all studies reported differences in the plasma BDNF levels between individuals with depression and the control patients." (PMID 33233633, 2020). "More, recent study provide growing evidence that brain-derived neurotrophic factor (BDNF), the most abundant eurotrophin in the brain and plasma, is related to suicidal behaviorin MDD and that BDNF level may be a biological marker of suicidal depression." (PMID 32398015, 2020). "Therefore, the restoration of BDNF/PI3K/Akt/mTOR expression by CYDXF may be attributed to, at least in part, the effects of regulating endocrine disorders and/or treating the depressive disorders of these bioactive compounds." (PMID 32265693, 2020). "The brain derived neurotrophic factor (BDNF) gene is expressed in the adult PFC, and plays a critical role in neural and behavioral plasticity, and the development of psychiatric disorders such as depression, bipolar disorder, and schizophrenia when coupled with ELA." (PMID 30984237, 2019). "Leptin can also increase the expression of BDNF mRNA, activate BDNF-expressing neurons, activate the PI3K-AKT-mTOR pathway to regulate the growth of neurons and regulate stress-induced depression and antidepressant response while reversing the dysfunction in the HPA axis." (PMID 31130833, 2019). "Furthermore, BDNF is involved in multiple processes relevant to sequela of TBI, including neuroprotection, epileptogenesis, memory and cognition, and mental health conditions such as depression and post-traumatic stress disorder (PTSD)." (PMID 31998207, 2019). "However, neither BDNF nor cortisol levels were predictors of major depression and none of the clinical characteristics of patients predicted their BDNF levels." (PMID 31231276, 2019). "Baseline serum BDNF alone could not predict depression severity, as the model was not significant (Binary logistic regression: X2 = 0.222, df = 1, p = 0.63; r2 Nagelkerke = 0.004)." (PMID 31231276, 2019).
depression (continued). "Although there was significant improvement in the depression score (60%), there was no variation in several plasma biomarkers including BDNF indicating that there is a complex relationship between the composition of the gut microbiota and its effect on neurogenesis and neuroplasticity metabolites." (PMID 31749681, 2019). "A recent research suggested a crosstalk between BDNF, Wnt/β-catenin and Shh signaling in chronic unpredictable mild stress (CUMS) induced prenatal stress and reported that the BDNF, β-catenin and Shh downregulates in depression and also decreases hippocampal neurogenesis." (PMID 31193084, 2019). "Similarly, 1,3,7-trihydroxyxanthone, a compound isolated from an herbal medicine that was used to treat forgetfulness and depression in ancient China, increases the expression of NGF and BDNF in cultured rat cortical astrocytes in a cAMP- and ERK-dependent manner." (PMID 30759771, 2019). "Dietary deprivation of n−3 PUFA for 15 weeks in rodents resulted in increased depression and aggression scores; this has been related to decreased phosphorylation of p38 MAPK, which in turn has been suggested to lead to decreased activation of CREB and reduced BDNF expression." (PMID 31098654, 2019). "Reduced serum BDNF levels, together with altered expression of BDNF and its high-affinity receptor tropomyosin receptor kinase B (TrkB) in the hippocampus and PFC, have been found in depression state and could be reversed by effective treatment with antidepressants." (PMID 32009956, 2019). "Aerobic exercise can lead to increases in BDNF concentrations which could, in turn, decrease the prevalence of non-motor depression and cognitive dysfunction symptoms." (PMID 31197095, 2019). "Multiple neurobiological and psychosocial factors, not controlled in our study, could also interfere with BDNF levels in depressive disorders in an inpatient psychiatric setting." (PMID 31572245, 2019). "This study showed increased BDNF mRNA levels in responders and significantly reduced H3K27me3 levels (a marker for silencing genes) at BDNF exon IV promoter, which showed a negative correlation with change in depression severity." (PMID 30459647, 2018). "We suggest that decrease in BDNF by the activated NLRP3 inflammasomes in astrocytes is the key pathological event of the depressive-like behaviors induced by SD, while the combined treatment with fluoxetine and leptin improves therapeutic outcome for the depression induced by SD." (PMID 30666218, 2018). "Interestingly, there was no significant change in BDNF levels in rats with depression-like phenotype or rats with anxiety-like phenotype as compared with the controls." (PMID 30740068, 2018). "In patients with major depressive disorder, an eight week moderate aerobic and resistance intervention significantly increased plasma BDNF concentrations while no change in serum BDNF concentrations were observed following a three month aerobic exercise intervention." (PMID 29686948, 2018). "Thus, this study suggests that the effect of MAI stimulation at SP6 might be attributable to changes in a pathway that is modulated by the BDNF-NPY system and relates to depression-like behaviors." (PMID 29643431, 2018). "The BDNF concentration in the serum exhibits negative correlation with Hamilton’s Depression Scale." (PMID 29845025, 2018). "This meta-analysis found decreased BDNF levels in both mania and depression, but not euthymia." (PMID 30113291, 2018). "In conclusion, endogenous n-3 PUFAs may improve LPS-induced depression-like behavior through balancing M1 and M2-phenotypes and normalizing BDNF function." (PMID 30248907, 2018). "Interestingly, in heterozygous BDNF+/- mice or in inducible BDNF KO lines of mice, deletion of BDNF in adults does not impact on depression-like behavior evaluated in the forced swim test (FST)." (PMID 30622454, 2018).
depression (continued). "Notably, we report the novel finding that MAI stimulation at SP6 relieves depression-like behavior through increased hippocampal BDNF rather than an increase in estrogen." (PMID 29643431, 2018). "Therefore, we hold our opinion that SI-rearing could induce the depression-like behavior, and the possible regulatory mechanism includes dysregulation of CORT and hippocampal BDNF insufficient." (PMID 28052034, 2017). "Similarly, serum levels of BDNF were lower in PD patients with depression than those without depression." (PMID 29255414, 2017). "Furthermore, we also found lower expression of BDNF in the rats with depression-like phenotype than rats without depression-like phenotype." (PMID 28600519, 2017). "Three hypotheses of pathogenesis of depression were adopted and validated in the present study, that is, (i) dysregulation of hypothalamic-pituitary-adrenal (HPA) axis, (ii) monoamine insufficient and (iii) hippocampal BDNF insufficient." (PMID 28052034, 2017). "Here, we report the effects of the retreat on BDNF, salivary cortisol, inflammatory cytokines (i.e., IL-1β, IL-6, IL-8, IL-12, IFN-γ, and TNF-α), IL-10, and psychological variables which included mindfulness, absorption, depression, anxiety and physical complaints." (PMID 28694775, 2017). "However, there is little evidence on the relationship between spinal GR and BDNF signaling under conditions of depression combined with neuropathic pain." (PMID 28579944, 2017). "Increased levels of BDNF protein in the brain are consistent with the efficacy of MAO inhibitors and electroconvulsive therapy and may be a predictor of the antidepressant action of interventions that are more effective in the treatment of major depression." (PMID 29299044, 2017). "However, the level of serum BDNF in the moderate depression group was not significantly different from the severe depression group (P = 0.673), which is consistent with the OS of the patients." (PMID 27852063, 2016). "Entered into a repeated mixed model for dependent variables were as follows: the BDNF values at follow-up of controls and persons with current depression episodes but not in full remission, partial remission or under treatment; and all available values of BDNF at baseline." (PMID 27070410, 2016). "However, initial exposure to CS during a late period of development (PND21) did not appear to affect depression-like behaviors and BDNF/TrkB in hippocampus, suggesting that a critical period of susceptibility exists during prenatal and early postnatal periods." (PMID 26503133, 2016). "Thus, it is likely that decreased BDNF-TrkB signaling in CA3, DG and PFC regions, precipitated by a deletion of the Nrf2 gene, may mediate depression-like phenotypes in Nrf2 KO mice." (PMID 27470577, 2016). "Cao L suggested that BDNF appears to be the most selectively responsive to a lack of depression and could therefore serve as a potential mediator of tumor resistance." (PMID 27852063, 2016). "We found that social defeat stress significantly decreased levels of BDNF protein in the PFC, DG, and CA3, but not in CA1, while significantly increasing BDNF protein in the NAc, consistent with previous data from the social defeat stress model of depression and the rat learned helplessness model." (PMID 27488193, 2016). "Analyses revealed that subjects that could not be included in the BDNF gene expression analyses, more often had a diagnosis of depression and/or anxiety than individuals that were not included (data not shown)." (PMID 27405617, 2016). "Interestingly, a 2-year longitudinal study showed a more profound decrease in serum BDNF levels in patients with persistent and remitted depression than in non-depressed controls." (PMID 27959329, 2016). "No study compared the role of BDNF Val66Met genotype in anxiety and depression." (PMID 26733829, 2015).
depression (continued). "Because an increase of BDNF in the hippocampus by chronic SSRI administration has been implicated in the mechanism of antidepressant action of SSRI,11, 12, 15 the lack of efficacy of paroxetine for METH-induced depression is of great interest." (PMID 26506052, 2015). "In analogy to major depression we hypothesized a decrease of BDNF and an increase of S100B, without changes of NSE in minor depression." (PMID 26500502, 2015). "Moreover, a higher level of BDNF has been observed in those Alzheimer’s patients showing symptoms of depression compared to those with no depressive symptoms." (PMID 26175754, 2015). "Similarly, presence of the history of major depression did not affect the levels of BDNF, S100B or NSE in the minor depression group (p = 0.10–0.50); neither in comparison with healthy controls (p = 0.13–0.38)." (PMID 26500502, 2015). "Other neural structures such as the insula may be involved in the link between maladaptive guilt and depression, but their anatomical and functional modulation by BDNF Val66Met and early trauma has not been studied." (PMID 26230319, 2015). "This could be demonstrated by the results that “Responders” to treatment (≥50% improvement in depression ratings) had higher pretreatment BDNF levels than did “Nonresponders”." (PMID 25821488, 2015). "Notably, as compared to a control group comprising subjects without depression, patients with depression show lower BDNF levels." (PMID 26405456, 2015). "The parallel comparison group revealed no significant changes in depression scores or BDNF levels." (PMID 26075212, 2015). "Although a large number of studies have determined serum BDNF levels using ELISA kits, the variability noted in overall mean BDNF levels irrespective of depression status might be reflective of pre-analytical conditions of BDNF assessment." (PMID 25886523, 2015). "Since BDNF levels do not correlate with depression severity, decreased serum BDNF might also be observed in minor depression." (PMID 26500502, 2015). "A negative relationship between stress and BDNF blood level is found in depression patients." (PMID 26091093, 2015). "Furthermore, blocking TrkB with ANA-12 in the NAc shell showed therapeutic effects on depression and behavioral sensitization after repeated METH exposure, confirming the role of the activated BDNF–TrkB signaling pathway in the mechanism of behavioral abnormalities after METH withdrawal." (PMID 26506052, 2015). "Our findings that CUS exposures decreased BDNF levels in mouse PFC and the treatment of M084 significantly reversed such a change in the CUS-exposed mice are entirely consistent with the current understanding about the contribution of the BDNF pathway in depressive disorders." (PMID 26317356, 2015). "However, similar to other transgenic mouse models of BDNF, these mice have not conclusively clarified the connection between BDNF and the pathophysiology of depression." (PMID 24817844, 2014). "Therefore, abnormal BDNF-TrkB signaling in the hippocampus, PFC, and NAc may play a role in inflammation-induced depression." (PMID 25628381, 2014). "However, the Val66Met polymorphism in humans has not provided any clear evidence that altered BDNF release plays a role in depression and anxiety in humans." (PMID 24817844, 2014). "The neurotrophic hypothesis of depression is based on the stress-induced downregulation and rapid-acting antidepressant-induced upregulation of BDNF and neuropeptide VGF (nonacronymic) expression in the brain." (PMID 25542689, 2014). "Furthermore, brain-derived neurotrophic factor (BDNF) plays an essential role in neuronal plasticity, with the downregulation of BDNF expression/function reproduced in a variety of animal models of depression." (PMID 25309465, 2014). "Thus, BDNF(±) mice do not show any clear baseline anxiety- or depression-like behaviors, but they are more vulnerable to stress and the effects of ADs are blocked in these mice." (PMID 24817844, 2014).